MMP26 (matrix metallopeptidase 26)
Description:
May hydrolyze collagen type IV, fibronectin, fibrinogen, beta-casein, type I gelatin and alpha-1 proteinase inhibitor. Is also able to activate progelatinase B.
Synonyms: endometase; MGC126590; MGC126592
Tractability: Small molecule: it belongs to a druggable protein family. Antibody: UniProt places it where antibodies can reach, with medium confidence; UniProt predicts a signal peptide or a membrane-spanning region; its Gene Ontology location is reachable by antibodies, with medium confidence. PROTAC: a small molecule that binds it is known.
Target class: Metallo protease; Metallo protease M10A subfamily; Metallo protease MAM clan; Protease; Enzyme
Gene: Protein-coding gene on chromosome 11 (4,704,784 to 4,992,431, forward strand). Ensembl gene ENSG00000167346.
Subcellular location: Secreted, extracellular space, extracellular matrix
Gene Ontology:
Molecular function: metalloendopeptidase activity; metallopeptidase activity; zinc ion binding
Biological process: negative regulation of inflammatory response; collagen catabolic process; extracellular matrix organization; proteolysis
Cellular component: extracellular matrix
Genetic constraint (gnomAD): Loss-of-function variants: 35 observed, 33.11 expected, observed/expected ratio (o/e) 1.06, 90% interval 0.81 to 1.4. The upper end of that interval is the gene's LOEUF score, 1.4, which puts it in group 5 of 6, group 1 being the genes least tolerant of losing a copy. Missense variants: 347 observed, 329.42 expected, observed/expected ratio (o/e) 1.05, 90% interval 0.96 to 1.15. Synonymous variants: 122 observed, 120.21 expected, observed/expected ratio (o/e) 1.01, 90% interval 0.88 to 1.18.
Homologues: Orthologues: chimpanzee MMP26 (98% identical), macaque MMP26 (93% identical), dog MMP26 (67% identical), rabbit MMP26 (62% identical), tropical clawed frog mmp8 (37% identical), zebrafish mmp13b (34% identical), Drosophila melanogaster Mmp1 (33% identical), zebrafish mmp25b (33% identical), zebrafish mmp25a (31% identical), zebrafish mmp30 (31% identical), Caenorhabditis elegans zmp-3 (31% identical), Caenorhabditis elegans zmp-6 (26% identical), and 7 more. Paralogues in human: MMP12 (41% identical), MMP13 (39% identical), MMP3 (38% identical), MMP7 (38% identical), MMP10 (37% identical), MMP9 (37% identical), MMP2 (36% identical), MMP27 (36% identical), MMP20 (36% identical), MMP8 (36% identical), MMP1 (35% identical), MMP15 (35% identical), and 11 more.
Diseases named in the same sentence as MMP26 in open-access papers:
MMP26 is named in the same sentence as 44 diseases in open-access papers, as found by Europe PMC text mining. Sharing a sentence is not in itself a finding about the gene and the disease. The quoted sentences say what the papers report.
prostate carcinoma (9 papers, 2005 to 2024). A carcinoma that arises from epithelial cells of the prostate gland. "For instance, SFMBT2 assisted in transcription suppression of MMP9 and MMP26, thereby inhibited metastasis of prostate cancer cells." (PMID 38734627, 2024). "Higher levels of MMP-26 in cancer patients compared to healthy individuals are also found in the course of other cancers such as breast cancer and prostate cancer." (PMID 38892452, 2024). "A prognostic model composed of seven protein-coding genes (FOXN4, MGAM, MMP26, ARC, SOX11, PRAME, and VWA5B2) was established, and it was strongly associated with biochemical recurrence following radical prostatectomy in prostate cancer." (PMID 37255653, 2022). "Among them, the expression of MMP-15 and MMP-26 correlated positively with Gleason score, but the biology and prognostic potential of these two MMPs need to be further investigated in prostate cancer." (PMID 24978435, 2014). "In cancer, MMP-26 expression is upregulated in human breast ductal carcinoma in situ, related to invasion 45, and in prostate cancer peaking of MMP-26 and TIMP-4 marks the invasive transition." (PMID 23634280, 2013). "In our model, MMP26 is the protective factor for the biochemical recurrence of prostate cancer." (PMID 37255653, 2022). "In addition to its direct proteolytic action on ECM substrates, MMP-26 has also been reported to be an activator of proMMP-9 in prostate cancer cells and correlated to MMP-9 activity in esophageal carcinoma." (PMID 20074375, 2010). "MMP-26 and TIMP-4 may play an important role in the transformation of high-grade prostatic intraepithelial neoplasia (HGPIN) to invasive carcinoma and may potentially act as diagnostic indicators for early prostate cancer." (PMID 37255653, 2022). "We showed that the expression level of SFMBT2 is critical for cell migration and invasion, which are fundamental features of prostate cancer malignancy through direct or indirect regulation of MMP-2, MMP-3, MMP-9, MMP-26, N-CoR, and KAI1 gene expression." (PMID 27340776, 2016). "In conclusion, our study provides evidence that SFMBT2 regulates prostate cancer metastasis either by direct repression of YY1 target genes such as MMP-9, MMP-26, and N-CoR and by indirect regulation of MMP-2, MMP-3, and KAI1 gene expression." (PMID 27340776, 2016). "Knockdown of SFMBT2 increases prostate cancer cell migration and invasion via direct repression of target genes such as MMP-9, MMP-26, and N-CoR in LNCaP and VCaP cells." (PMID 27340776, 2016). "MMP-26 has been shown to activate pro-MMP-9, thereby promoting invasion of prostate cancer cells." (PMID 27340776, 2016).
breast carcinoma (7 papers, 2005 to 2025). "It is known that MMP-26 is involved in the development of oestrogen-dependent cancers, including breast cancer." (PMID 33916127, 2021). "Matrilysins (MMP-7 and MMP-26) are members of the MMPs group that show promise as potential breast cancer (BC) markers." (PMID 33916127, 2021). "MMP-26 has been indicated to associate with a wide range of pathological process, such as breast cancer, glioma, wounds and ischemic stroke, but lack of evidence highlights necessity of further investigation of this gene." (PMID 35444067, 2022). "However, since the study is not related to breast cancer and there are no other reports on the subject in the available literature, we were unable to compare our findings regarding MMP-26 or both enzymes with the research of other authors." (PMID 33916127, 2021). "This is partly in accordance to our results, as we did not detect MMP-26 mRNA in breast cancer tissue G2 and G3, though we could not detect MMP-26 mRNA in normal breast tissue either." (PMID 19531263, 2009).
endometrial cancer (6 papers, 2010 to 2025). Primary or metastatic malignant neoplasm involving the endometrium (mucous membrane that lines the endometrial cavity). "The role of MMPs, especially MMP-7 and MMP-26, in the pathogenesis of endometrial cancer involves several related mechanisms." (PMID 40332487, 2025). "Also, increased expression of MMP-26 has been observed in endometrial cancer relative to healthy tissues, with it being higher with advanced tumor stage and depth of invasion." (PMID 41007705, 2025). "We investigated the levels of MMP-7, MMP-26, MMP-3, and MMP-10 in comparison with the levels of a tumor marker (CA125) in the plasma of postmenopausal patients in early stages of endometrial cancer (EC) compared with control groups: patients with benign lesions (myoma uteri) and healthy controls." (PMID 40332487, 2025). "Current research shows that endometrial cancer expresses more TIMPs (Tissue Inhibitors of Metalloproteinases), including MMP26 (Matrix Metalloproteinase 26), TIMP-3 (Tissue Inhibitor of Metalloproteinases-3), and TIMP-4(Tissue Inhibitor of Metalloproteinases-4)." (PMID 38782818, 2024). "Our study found that the expression of MMP26 in EECs was 22.74-fold higher than in ESCs, but it could not be detected in the endometrial carcinoma cell line RL95–2 (data not shown)." (PMID 27143441, 2016). "Consequently, in our study none of the tested endometrial cancer cell lines was positive for MMP-26 mRNA." (PMID 20942921, 2010).
ovarian carcinoma (5 papers, 2021 to 2025). A malignant neoplasm originating from the surface ovarian epithelium. "We also found one work that describes the diagnostic utility values for MMP-11 and MMP-26 in patients with ovarian cancer." (PMID 41007705, 2025). "Statistically significant positive correlations in the ovarian cancer group were observed between MMP-26 and MMP-10 (r = 0.2168; p = 0.0101)." (PMID 40565125, 2025). "In conclusion, we are the first team to study the significance of MMP-2, MMP-3, MMP-11 and MMP-26 as new markers of ovarian cancer in comparison not only to HE4 and CA125, but also to the ROMA algorithm." (PMID 38892452, 2024). "However, there are studies available on this MMP in other gynecological cancers; e.g., in the case of endometrial or ovarian cancer, higher concentrations of MMP-26 were demonstrated when compared to healthy women." (PMID 41462922, 2025). "The purpose of the present study was to determine the diagnostic utility of selected MMPs, MMP-2, MMP-3, MMP-11 and MMP-26, as new biomarkers in patients with ovarian cancer and to compare the results obtained with routinely determined markers CA125 and HE4 and the ROMA algorithm." (PMID 38892452, 2024). "The presence of MMP-7, MMP-26, MMP-3, MMP-10, and MMP-11 expression has been previously confirmed in biopsy material from ovarian cancer patients." (PMID 41007705, 2025). "Ovarian cancer patients have elevated concentrations of MMP-7, MMP-26, MMP-10 as well as CA125 and HE4 in the total group and subgroups (stage I + II, and III + IV)." (PMID 40565125, 2025). "The immunostaining intensity of MMP-26 increased with ovarian tumour stage, which suggests a role for MMP-26 in ovarian cancer biological function." (PMID 34645493, 2021). "MMP-2, MMP-3, MMP-11 and MMP-26 have not shown potential as stand-alone biochemical markers in ovarian cancer diagnosis." (PMID 38892452, 2024). "Therefore, the aim of this study was to evaluate the concentrations and diagnostic usefulness of selected enzymes from the matrilysin group (MMP-7, MMP-26) and stromelysins (MMP-3 and MMP-10) in the most common histological type of ovarian cancer—the serous type." (PMID 40565125, 2025).
breast ductal carcinoma in situ (2 papers, 2008 to 2013). "Additionally, MMP-26 is inhibited by the same group of TIMPs, and the co-expression of these proteins has been observed in endometrial carcinoma and in breast ductal carcinoma in situ (DCIS)." (PMID 19025595, 2008).
colon cancer (2 papers, 2004 to 2013). "During the preparation of this manuscript, two other MMPs, MMP26 and MT1-MMP, were identified in colon cancer as β-catenin targets." (PMID 15054469, 2004).
endometriosis (2 papers, 2020 to 2025). The growth of functional endometrial tissue in anatomic sites outside the uterine body. "MMP-7 and MMP-26 are usually expressed in healthy female endometria and in various uterine lesions, such as endometriosis and myomas." (PMID 40332487, 2025). "SPP1, LIF, TCN1 and CLDN4 were common to adenomyosis and healthy groups of genes, while ANXA2, EDNR8, MMP26, DEPP1, ABCC3, CDA and SLC1A1 were common to endometriosis and healthy groups." (PMID 32933042, 2020).
glioma (2 papers, 2022). A benign or malignant brain and spinal cord tumor that arises from glial cells (astrocytes, oligodendrocytes, ependymal cells). "In addition, CHLA-02 expressed a high level of MMP-26, an invasion biomarker in various cancers, including gliomas, astrocytic gliomas, colorectal cancer, and esophagus squamous cell carcinomas." (PMID 35954348, 2022).
Infertility (2 papers, 2016 to 2019). "However, there are also studies which demonstrated that MMP26 was significantly increased in women with unexplained infertility compared with fertile women." (PMID 31275970, 2019).
invasive carcinoma (2 papers, 2009 to 2022). A carcinoma that is not confined to the epithelium, and has spread to the surrounding stroma. "Further, on tumor progression to invasive carcinomas the expression level of MMP-26 was described to decrease again." (PMID 19531263, 2009).
ischemic stroke (2 papers, 2019 to 2022). A stroke disorder caused by obstruction of blood flow to the brain, due to thrombotic (local blood clot formation) or embolic (due to a blood clot or other material traveling from another site) event. "In our study, the wGRS summarizing the influence of MMP-7, MMP-8 and MMP-26 was associated with ischemic stroke." (PMID 31752174, 2019). "Although the results from our study need to be replicated in other studies, our data suggest that a cumulative effect of genetic variants from MMP-7, MMP-8 and MMP-26 on the risk of ischemic stroke." (PMID 31752174, 2019). "In summary, we found that a wGRS that includes variants of MMP-7, MMP-8 and MMP-26 was associated with increased risk of ischemic stroke." (PMID 31752174, 2019). "Additionally, MMP8 rs3740938, rs1940475, rs11225395 and MMP26 rs2499966 were associated with ischemic stroke in recessive models." (PMID 31752174, 2019). "There was a significant interaction between high genetic and high modifiable CVD risk, indicating that the combined genetic risks from MMP-7, MMP-8 and MMP-26 may modify the association of high modifiable CVD risk with ischemic stroke." (PMID 31752174, 2019).
benign breast tumour (1 paper, 2021). "The concentrations of MMP-7, MMP-26 and CA 15-3 in the BC group were significantly higher than in the total control group (benign breast tumour subjects and healthy controls) (p < 0.001)." (PMID 33916127, 2021). "Median levels of MMP-7, MMP-26 and CA 15-3 in the total BC group were higher than in the benign breast tumour group (p = 0.013; p = 0.015; p = 0.003, respectively)." (PMID 33916127, 2021).
cervical cancer (1 paper, 2025). A primary or metastatic malignant neoplasm involving the cervix. "MMP-26 also displayed elevated concentrations in cervical cancer patients compared to controls, although the increase was less pronounced." (PMID 41462922, 2025). "Our data on MMP-26 in cervical cancer are the first such reports." (PMID 41462922, 2025). "Unfortunately, there are no available papers describing the diagnostic utility or even tissue/gene expression of MMP-26 in cervical cancer; therefore, we are not able to compare our results with those of other authors." (PMID 41462922, 2025).
chondrosarcoma (1 paper, 2023). A malignant cartilaginous matrix-producing mesenchymal neoplasm arising from the bone and soft tissue. "Xu and coworkers have recently shown that the overexpression of the matrix metalloproteinase-26 (MMP26) increased the invasiveness of chondrosarcoma cells." (PMID 37681914, 2023).
dysplasia (1 paper, 2025). A usually neoplastic transformation of the cell, associated with altered architectural tissue patterns. "In our study we tried to assess the potential of MMP-3, MMP-7, MMP-10, and MMP-26, which showed significant differences in concentrations between the groups of healthy women, dysplasia patients, and cancer patients, and also demonstrated the ability to distinguish benign from malignant lesions." (PMID 41462922, 2025). "In the case of MMP-26, the highest concentrations and those increasing with advancement were observed in CC, moderate concentrations in the healthy group (HG), and the lowest in the group of women with diagnosed dysplasia." (PMID 41462922, 2025).
endometrioid ovarian cancer (1 paper, 2025). "In the case of MMP-26, similarly to MMP-10, higher levels of this enzyme were found in patients with ovarian cysts (10,985 pg/mL) compared to patients with endometrioid ovarian cancer (9425 pg/mL) and healthy women (7163 pg/mL)." (PMID 41007705, 2025).
Ovarian cyst (1 paper, 2025). The presence of one or more cysts of the ovary. "Clinically elevated MMP-26 levels in patients with ovarian cysts may indicate the enzyme’s involvement in extracellular matrix remodeling and the local inflammatory response associated with benign lesions." (PMID 41007705, 2025).
Serous Ovarian Carcinoma (1 paper, 2025). "The tested matrilysins MMP-7 and MMP-26 and stromelysin MMP-10 have the highest initial diagnostic potential in detecting High-Grade Serous Ovarian Carcinoma." (PMID 40565125, 2025). "Of the MMPs tested, MMP-7, MMP-26, and MMP-10 have the highest potential in diagnostics of serous ovarian cancer patients." (PMID 40565125, 2025).
sickle cell disease (1 paper, 2025). Sickle cell anemias are chronic hemolytic diseases that may induce three types of acute accidents: severe anemia, severe bacterial infections, and ischemic vasoocclusive accidents (VOA) caused by sickle-shaped red blood cells obstructing small blood vessels and capillaries. "We identified 7 loci-drug ADE pairs including an association between rs73407039 in MMP26 and morphine ADE that is consistent with higher frequency of morphine use among individuals with sickle cell disease." (PMID 41282679, 2025).